PIN1P1 (peptidylprolyl cis/trans isomerase, NIMA-interacting 1 pseudogene 1)
Synonyms: formerly PIN1L
Gene: Transcribed processed pseudogene on chromosome 1 (69,919,357 to 69,919,657, forward strand). Ensembl gene ENSG00000229359.
Diseases named in the same sentence as PIN1P1 in open-access papers:
PIN1P1 is named in the same sentence as 5 diseases in open-access papers, as found by Europe PMC text mining. Sharing a sentence is not in itself a finding about the gene and the disease. The quoted sentences say what the papers report.
gastric cancer (1 paper, 2024). A primary or metastatic malignant neoplasm involving the stomach. "High expression of PIN1P1 was associated with worse overall survival and rapid progression in patients with gastric cancer." (PMID 37929660, 2024). "Our findings offer insights into the mechanisms underlying pseudogene lncRNA‐associated gastric carcinoma progression and lay the foundation for further PIN1P1/PIN1‐targeting therapeutical approaches for gastric cancer." (PMID 37929660, 2024). "The results of CCK8 and EdU proliferation assays demonstrated that PIN1P1 overexpression enhanced gastric cancer proliferation capabilities, whereas knockdown of PIN1P1 restrained cell proliferation." (PMID 37929660, 2024). "Here, we investigated a novel lncRNA, PIN1P1, upregulated in gastric cancer and transcriptionally activated by CREB1." (PMID 37929660, 2024). "PIN1P1 was overexpressed in gastric cancer tissues, and upregulated PIN1P1 predicted poor prognosis in patients." (PMID 37929660, 2024). "PIN1P1 expression in gastric cancer tissues showed a positive relationship with PIN1 expression (Spearman r = 0.5079, p < 0.0001)." (PMID 37929660, 2024). "Here, we show that lncRNA PIN1P1 is one of the direct target genes of CREB1 in gastric cancer and is transcriptionally activated by CREB1." (PMID 37929660, 2024). "The subcellular distribution of PIN1P1 was determined, and PIN1P1 was mainly found in the nucleus of gastric cancer cells." (PMID 37929660, 2024). "Compared to the normal gastric mucosas, PIN1P1 was increased in gastric cancer tissues, especially in those with lymph node metastasis (LNM)." (PMID 37929660, 2024). "PIN1, the parental gene of PIN1P1, was elevated in gastric cancer tissues, and its upregulation was correlated with poor patient outcomes." (PMID 37929660, 2024). "Overexpressed PIN1P1 promoted the proliferation, migration and invasion of gastric cancer cells, whereas decreased PIN1P1 showed the opposite effects." (PMID 37929660, 2024). "The results of the actinomycin D chase assay showed that PIN1P1 was more stably expressed than short half‐life c‐Myc mRNA in gastric cancer cells, suggesting the possibility of PIN1P1 as a stable biomarker in gastric cancer." (PMID 37929660, 2024). "Herein, a previously undescribed oncogenic lncRNA derived from the pseudogene PIN1P1 was confirmed to be upregulated in gastric cancer." (PMID 37929660, 2024). "And through rescue experiments, we found that PIN1P1 is a functional target of CREB1 in promoting the tumorigenesis of gastric cancer." (PMID 37929660, 2024). "We reveal that the pseudogene PIN1P1 promotes the progression of gastric cancer by interacting with YBX1 and activating PIN1." (PMID 37929660, 2024). "Here, the expression of PIN1P1 was analysed in another 60 cases of gastric cancer tissues and eight normal gastric mucosas through RT‐qPCR." (PMID 37929660, 2024). "PIN1P1 was overexpressed by transfection with the PIN1P1 overexpression plasmid or knocked down by the PIN1P1 antisense oligonucleotide (ASO), with the aim of examining the effect of PIN1P1 on gastric cancer cells." (PMID 37929660, 2024). "In conclusion, lncRNA PIN1P1 has been identified as an effector of gastric cancer progression and is transcriptionally induced by CREB1." (PMID 37929660, 2024). "The mechanistic model of PIN1P1 in gastric cancer was further explored by RNA pull‐down, RIP and western blot analysis." (PMID 37929660, 2024). "The expression and effects of lncRNA PIN1P1 in gastric cancer were investigated." (PMID 37929660, 2024). "Association between PIN1P1 or PIN1 expression and clinicopathological parameters in gastric cancer." (PMID 37929660, 2024). "PIN1P1 was upregulated in gastric cancer tissues compared to normal gastric mucosas." (PMID 37929660, 2024). "Downregulation of p27 upon PIN1P1 overexpression is consistent with the findings that PIN1P1 could promote cell proliferation in gastric cancer." (PMID 37929660, 2024).
gastric cancer (continued). "Here we found that in gastric cancer, PIN1P1 interacted with YBX1, upregulating its protein expression, which in turn enhanced the expression of PIN1, in which transcription factor E2F1 may be involved." (PMID 37929660, 2024). "Furthermore, the expression of CREB1 in gastric cancer tissues was positively related to PIN1P1 expression (Spearman r = 0.5168, p < 0.0001)." (PMID 37929660, 2024). "Moreover, PIN1P1 facilitated proliferation, migration and invasion of gastric cancer cells." (PMID 37929660, 2024). "However, the role and mechanism of the pseudogene lncRNA PIN1P1 in gastric carcinoma remain unclear." (PMID 37929660, 2024). "We have previously performed a genome‐wide screening of CREB1 targets by ChIP‐seq in gastric cancer cells (GEO database GSE220708) and found numerous targets of CREB1, in which PIN1P1 was involved." (PMID 37929660, 2024). "High expression of PIN1P1 was positively related to LNM, tumour size, tumour stage and the poor outcome of patients with gastric cancer." (PMID 37929660, 2024). "As we have shown that PIN1P1 could promote PIN1 expression, we next explored the expression of PIN1 in gastric cancer tissues and its function in gastric cancer cells." (PMID 37929660, 2024). "PIN1P1 was identified to directly bind to the YBX1 protein, which may mediate PIN1 upregulation and promote gastric cancer progression." (PMID 37929660, 2024). "It was confirmed that PIN1P1 could promote gastric cancer cell proliferation, migration and invasion, which is consistent with the oncogenic effects of PIN1 in gastric cancer." (PMID 37929660, 2024). "The biological function of PIN1P1 in gastric cancer has not been reported previously." (PMID 37929660, 2024).
cancer (1 paper, 2024). A tumor composed of atypical neoplastic, often pleomorphic cells that invade other tissues. "However, the expression and function of PIN1P1 in human diseases, including cancers, and the effect of PIN1P1 on its parental gene PIN1 have not yet been documented." (PMID 37929660, 2024). "PIN1P1 is the pseudogene of the critical oncogene PIN1, but has not yet been investigated in human cancer." (PMID 37929660, 2024).
PIN1P1 also shares sentences with these, for which no sentence is quoted: Tumor (2 papers); cholangiocarcinoma (1); lymph node metastasis (1).